VDR (vitamin D receptor)
Diseases named in the same sentence as VDR in open-access papers (continued):
Sharing a sentence is not in itself a finding about the gene and the disease.
breast cancer (continued). "In the present study we investigated the risk of breast cancer in relation to sun exposure and its interaction with VDR gene variants among wives of farmers in a large, prospective, two-state agricultural cohort." (PMID 24252436, 2014). "A few studies have investigated the association of VDR polymorphisms with breast cancer survival, but their results were also inconsistence." (PMID 24769568, 2014). "In conclusion, this comprehensive meta-analysis of high-quality studies provides substantial evidence that the Fok1 polymorphism in the VDR gene is significantly associated with an increased risk of developing breast cancer." (PMID 24769568, 2014). "Other studies have reported no modification of associations between measured or inferred vitamin D status and breast cancer by the VDR polymorphisms BsmI, FokI, TaqI, or ApaI (rs7975232, also evaluated in the present study)." (PMID 24252436, 2014). "Our meta-analysis illustrates strong evidence for the association between a VDR gene polymorphism in Fok1 and an increased risk of breast cancer." (PMID 24769568, 2014). "Studies that have examined interactions between VDR variants and markers of vitamin D—including sun exposure, serum 25(OH)D, and dietary vitamin D intake—on breast cancer risk have produced inconsistent, but largely null, results." (PMID 24252436, 2014). "To clarify the association between breast cancer risk and VDR gene polymorphisms, we performed a meta-analysis of 39 existing studies to clarify the relationship between genetic variations in VDR and the risk of breast cancer." (PMID 24769568, 2014). "The important roles that VDR polymorphisms play in the pathogenesis of breast cancer have been investigated across the world." (PMID 24769568, 2014). "Here, we aimed to assess the correlation between the different alleles of VDR gene polymorphisms and renal cell cancer and breast cancer risks separately through a systematic review of the present literature." (PMID 24297042, 2014). "Characteristics of studies included in the meta-analysis of the relation between the Fok1,Poly A, Bsm1,Taq1 and Apa1 polymorphisms in the vitamin D receptor gene and breast cancer." (PMID 24769568, 2014). "We estimated interactions between sun exposure, VDR variants, and breast cancer in a nested case–control study comprising 293 cases and 586 matched controls." (PMID 24252436, 2014). "Many studies have been carried out to investigate the relationship between VDR gene polymorphisms and the risk of breast cancer." (PMID 24769568, 2014). "In contrast, this analysis has revealed that some VDR gene polymorphisms, such as: Bsm1, poly(A), Taq1, Apa1, are to some extent associated with breast cancer risk." (PMID 24297042, 2014). "In this study we have analyzed the polymorphisms in the VDR gene occurring most commonly in breast cancer and renal cancer." (PMID 24297042, 2014). "Sun exposure, vitamin D receptor genetic variants, and risk of breast cancer in the Agricultural Health Study." (PMID 24252436, 2014). "The VDR-TaqI (tt genotype) and VDR-ApaI (a allele) were significantly associated with breast cancer in only two hospital-based studies." (PMID 23554871, 2013). "Associations between VDR polymorphisms and risk of breast cancer are complex and warrant further research." (PMID 23533810, 2013). "In a case–control study, female breast cancer patients and a female control group (n=604) were tested for two VDR polymorphisms." (PMID 29805854, 2013). "Although African-Americans have the lowest levels of serum vitamin D, there is a dearth of information on VDR gene polymorphisms and breast cancer among African-Americans and Hispanics." (PMID 23554871, 2013). "The results from our study reveal an increased association between one of the VDR polymorphic variants, VDR-FokI, and breast cancer in the African-American cohort." (PMID 23554871, 2013).
breast cancer (continued). "This is consistent with other studies which have identified a positive association between the VDR-FokI ff genotype and/or f allele and breast cancer." (PMID 23554871, 2013). "Vitamin D receptor (VDR) gene polymorphisms have also been shown to modify breast cancer susceptibility." (PMID 23341935, 2013). "We have examined four VDR polymorphisms (FokI, TaqI, BsmI, ApaI) in African-American and Hispanic women from South Los Angeles and their association with breast cancer risk and survival." (PMID 23554871, 2013). "Another study found that FokI genotype influenced breast cancer risk when accounting for other VDR polymorphisms in haplotype combinations." (PMID 23533810, 2013). ": Although the factors that increase breast cancer susceptibility remain uncertain, future large studies should integrate genetic variation in VDR with biomarkers of vitamin D status." (PMID 29805854, 2013). "The odds ratio (OR) for breast cancer in association with the VDR-FokI f allele was 1.9 (95% CI = 0.9–3.7; p = 0.07)." (PMID 23554871, 2013). "Large meta-analyses have demonstrated a significant association of the VDR FokI polymorphisms with breast cancer, and other cancers across multiple ethnic cohorts." (PMID 23554871, 2013). "In terms of the ApaI polymorphism in the VDR gene, the Aa and aa genotypes were associated with about a 1.5-fold increased breast cancer risk." (PMID 23533810, 2013). "An increased association of the VDR-Fok1 f allele with breast cancer was observed in African-Americans (OR = 1.9, p = 0.07)." (PMID 23554871, 2013). "Two common single nucleotide polymorphisms (SNP) in the VDR gene (VDR), rs1544410 (BsmI) and rs2228570 (FokI), have been inconsistently associated with breast cancer risk." (PMID 29805854, 2013). "The VDR-FokI FF genotype is linked with poor prognosis in African-American women with breast cancer." (PMID 23554871, 2013). "To date, three studies have examined selected SNPs in VDR with breast cancer risk in both AA and EA women." (PMID 22480149, 2012). "Polymorphisms in the VDR gene have been analyzed for their associations with prostate cancer, breast cancer, colorectal adenomas and also for their association with melanomas." (PMID 22576141, 2012). "To confirm these findings, we conducted an experiment with MDA-MB231 human breast cancer cells transiently overexpressing the two different VDR variants under identical conditions and found similar results (VDRff treatment vs VDRFF treatment, P<0.01)." (PMID 21283672, 2011). "This is the first report documenting a differential response to 1,25D3 in relation to cell proliferation, transactivation of vitamin D target gene, CYP24A1 and modulation of estrogen receptor signaling among the two VDR alleles in breast cancer cells." (PMID 21283672, 2011). "Collectively, these results imply that VDRFF cells are more sensitive to vitamin D treatment compared to VDRff cells and provide a platform for further examining the functional significance of the FokI VDR polymorphism in human breast cancer." (PMID 21283672, 2011). "The FokI polymorphism, either singly or in combination with other VDR polymorphisms, has been extensively investigated in breast cancer risk assessment studies." (PMID 21283672, 2011). "In a haplotype analysis, we found the haplotype FtCA (FokI F, TaqI t, VDR-5132 C, Cdx2 A) to be associated with a significantly greater breast cancer risk as compared with the most frequent haplotype (FTCG)." (PMID 18419802, 2008). "In a haplotype analysis the haplotype FtCA (FokI F, TaqI t, VDR-5132 C, Cdx2 A) was associated with a significantly higher breast cancer risk as compared with the most frequent haplotype (FTCG)." (PMID 18419802, 2008). "Our results support potential effects of VDR polymorphisms on postmenopausal breast cancer risk and possible differential effects of receptor status of the tumour." (PMID 18419802, 2008).
breast cancer (continued). "We therefore assessed the association of FokI, TaqI, VDR-5132 and Cdx2 SNPs and their associated haplotypes with postmenopausal breast cancer risk and possible effect modification by serum 25(OH)D in this study population." (PMID 18419802, 2008). "We examined the association between polymorphisms in the 3' end of the VDR gene, specifically BsmI and Poly(A), and breast cancer risk within a large, population-based, case-control study of breast cancer." (PMID 18067661, 2007). "One of the largest, that conducted by Chen and colleagues, was conducted to investigate the role played by VDR polymorphisms and breast cancer risk in a nested case-control study of largely Caucasian women aged 43 to 69 years within the Nurses' Health study." (PMID 18067661, 2007). "Few studies have examined interactions between dietary factors and VDR polymorphisms in relation to breast cancer risk." (PMID 17244366, 2007). "In our study, dietary calcium intake, but not vitamin D intake, significantly modified the association between VDR SNPs near the 3' end of the gene and breast cancer risk." (PMID 17244366, 2007). "In analyses stratified by dietary factors, total calcium intake (but not vitamin D intake) modified the associations between polymorphisms near the 3' end of the VDR and breast cancer risk." (PMID 17244366, 2007). "In one case-control study in the UK, women with low plasma 25(OH)D levels and the BsmI bb VDR genotype had a 6.8-fold higher risk of breast cancer than individuals with higher 25(OH)D levels and the BB or Bb genotype." (PMID 17244366, 2007). "The VDR polymorphism BsmI, an intronic 3′ gene variant, was significantly associated with increased breast cancer risk: odds ratio bb vs BB genotype = 2.32 (95% CI, 1.23–4.39)." (PMID 11461072, 2001). "The active form of vitamin D, 1,25(OH)2D, is responsible for the activation of VDR, therefore, circulating 25(OH)D could potentially have an inverse association with breast cancer risk." (PMID 39061008, 2024). "Further, this study aimed to explore whether the associations between VDR and prognosis differ between subgroups of breast cancer." (PMID 38612962, 2024). "VDR genotypes were associated with breast cancer prognosis and the association might be modified by tumor size." (PMID 38351438, 2024). "Since breast cancer diagnostics today not only relies on microscopic evaluation by pathologists, other methods besides immunohistochemistry, such as gene expression analysis, should be further explored for associations between the VDR and breast cancer outcomes." (PMID 38612962, 2024). "We first checked whether intestinal epithelial VDR deletion has any effects on the microbiome and the risk of breast cancer." (PMID 37074210, 2023). "Nevertheless, there were indications that women with high levels of vitamin D were less likely to develop a breast tumor with low VDR expression, compared to women with low levels of vitamin D. Low pre-diagnostic levels of vitamin D were associated with an increased breast cancer mortality." (PMID 36014861, 2022). "Interestingly, polymorphisms in vitamin D pathway-related genes have been shown to be associated with risk of breast cancer, specifically the FokI variant of VDR that confers risk when it coincides with other breast cancer risk genotypes." (PMID 35807774, 2022). "Secondly, this study aimed to investigate whether an association found between VDR expression and breast cancer mortality was influenced by pre-diagnostic systemic levels of vitamin D." (PMID 36014861, 2022). "Heterogeneity of breast cancer also involves differences between specific breast compartments, which cause differential distribution of vitamin D3 in different regions of breast tumors due to different activity of enzymes involved in vitamin D3/VDR signaling." (PMID 35328609, 2022). "As presented in Section 2, many miRNAs may be implicated in the regulation of the vitamin D3/VDR axis in breast cancer." (PMID 35328609, 2022).
breast cancer (continued). "A possible explanation for the reported association between pre-diagnostic vitamin D levels and breast cancer mortality may be that the levels of vitamin D affect the expression of VDR in subsequent breast tumors." (PMID 36014861, 2022). "Breast cancer tissues showed extensive heterogeneity and variability (particularly in the shorter variants, which are barely detectable in normal tissue) and expressed markedly lower levels of full‐length VDR transcripts." (PMID 34950835, 2021). "Moreover, nuclear VDR positivity in LumB-like tumors is found to be significantly associated with a decreased risk of breast cancer death and seemingly resembled the HR3 positive groups (LA/LB) with good prognosis." (PMID 34771496, 2021). "Thus, activation of VDR is predictive of reduced risk of breast cancer recurrence in ER+ patients, possibly by inhibiting antiestrogen-promoted pro-survival autophagy." (PMID 34069442, 2021). "Anticancer properties of vitamin D3 postulated that sequence level variations in the VDR gene may alter breast cancer risk either exclusively or via gene–gene or gene–environment interactions." (PMID 34727991, 2021). "Thus, changes in the levels of miR-125b is an indirect predictor of VDR expression levels and its subsequent role in the risk stratification of breast cancer patients." (PMID 34771496, 2021). "Although it was shown that breast cancer cells have elevated expression of VDR, they produce exotic receptor variants (V3, V1d′′) and less full-length variants (V1, V2, V1d, V1d′); truncated, downstream aberrant variants (yet unnamed) contribute to much of the VDR-related mRNA production." (PMID 34638264, 2021). "Different results from different studies indicate that the association of VDR gene polymorphisms with breast cancer risk may be affected by some factors including race, diet, lifestyle, and environmental factors." (PMID 32986367, 2020). "In our study, the absence of baseline data such as sunlight exposure, skin color, and family history may affect the accuracy of the association of TaqI and ApaI polymorphisms in the VDR gene with breast cancer risk." (PMID 32986367, 2020). "Although VDR may frequently be retained in breast tumors, many women with breast cancer are vitamin D deficient." (PMID 32774770, 2020). "We found that positive VDR expression in the nuclei and cytoplasm of breast cancer cells was associated with favorable tumor characteristics such as smaller size, lower grade, estrogen receptor positivity and progesterone receptor positivity, and lower expression of Ki67." (PMID 31358030, 2019). "Since women with intermediate vs low levels of vitamin D may have a better survival following breast cancer, it could be assumed that VDR expression in breast tumors is also associated with a better prognosis." (PMID 31358030, 2019). "However, reports regarding the specific relevance of VDR allelic variations on breast cancer risk have been inconsistent." (PMID 30699973, 2019). "The prevalence of different VDR variants among breast cancer women could explicate, in part, certain inconsistencies seen in the response to vitamin D in several markers of breast cancer." (PMID 31350967, 2019). "In conclusion, our results indicate that changes in inflammatory biomarkers (plasma MMP9 and TNFα) associated with breast cancer risk and survival in breast cancer survivors with low plasma 25(OH)D levels, supplemented with vitamin D3 depends on VDR SNPs (Cdx2, TaqI and BsmI) and haplotypes." (PMID 31167402, 2019). "There may be specific vitamin D receptor gene polymorphisms associated with breast cancer risk in Asian women." (PMID 31884419, 2019). "We investigated whether vitamin D receptor (VDR) polymorphisms are associated with circulating metabolic biomarkers and anthropometric measures changes in breast cancer survivors supplemented with vitamin D3." (PMID 31395070, 2019).
breast cancer (continued). "The hypothesis was that breast cancers with VDR expression would be associated with less aggressive tumors and a low risk of breast cancer death, i.e., a better survival." (PMID 31358030, 2019). "Genetic variations in the VDR genes have also been associated to risk of breast cancer." (PMID 30699973, 2019). "In addition, both intranuclear and cytoplasmic VDR expression were associated with a low risk of breast cancer mortality, hazard ratios 0.56 (95% CI 0.34–0.91) and 0.59 (0.30–1.16) respectively." (PMID 31358030, 2019). "TaqI, one of the VDR polymorphism, reduced the risk of breast cancer by 26%." (PMID 31350967, 2019). "The genetic constitution of Ethiopians could also add pertinent information related to the role of VDR gene polymorphism in breast cancer susceptibility." (PMID 30699973, 2019). "The explanation of this association may reside in the increased vitamin D receptor (VDR) expression in breast cancer tumors of all phenotypes, making them good targets for calcitriol anticancer effects." (PMID 31698751, 2019). "For example, VDR function to transactivate CAMP is influenced by the VDR single nucleotide polymorphism (SNP) FokI (rs2228570) and ethnicity, while vitamin D insensitivity in breast cancer cells has been attributed to CpG methylation of the VDR primary promoter." (PMID 28959253, 2017). "The molecular mechanisms underlying the down-regulation of KCa1.1 through the VDR signaling pathway in breast cancer cells has yet to be elucidated; however, epigenetic modifications and protein degradation via proteasome pathways represent possible mechanisms." (PMID 27973439, 2016). "Cdx2 VDR polymorphism can play an important role in breast cancer, modulating the activity of VDR." (PMID 25849303, 2015). "Furthermore, the potential relationship among Cdx2 VDR polymorphism and a number of biomarkers used in clinical management of breast cancer was assessed in an ad hoc set of breast cancer cases." (PMID 25849303, 2015). "The frequency of the A allele is 74% in Africans, 43% in Asians and 19% in Caucasians.The A allele allows the Cdx2 transcription factor to bind more effectively, thereby increasing VDR transcriptional activity thus decreasing the breast cancer incidence, whereas the G allele has the opposite effect." (PMID 25799416, 2015). "However, the published data examining the relationship between VDR Cdx2 variants and breast cancer susceptibility have been contradictory." (PMID 25799416, 2015). "A study from Iran lends support to an increased risk of breast cancer associated with the VDR-BsmI polymorphism; one Chinese study says that VDR gene polymorphisms may be potential risk factors for prostate cancer." (PMID 25649962, 2015). "Associations of the BsmI and FokI SNPs in the VDR gene with breast cancer risk and histopathological tumor parameters were examined in a data set from women participating in a large hospital-based PAK-BCCC study that included 463 genetically enriched breast cancer cases and 1,012 controls." (PMID 26517870, 2015). "The GG genotype of VDR-Cdx2 polymorphism may increase the risk of breast cancer in females from Karachi, Pakistan." (PMID 25799416, 2015). "It has been previously demonstrated that VDR expression is reduced in cancer cells, which may be influenced by polymorphisms within the gene and increase breast cancer incidence." (PMID 25799416, 2015). "As vitamin D exerts its activity by binding to the VDR, the finding that normal breast epithelial cells and most breast cancer cells express VDR suggests the possibility that VDR gene polymorphism may be associated with breast cancer risk." (PMID 24769568, 2014). "Therefore, in this review we aimed to assess the correlation between the different alleles of VDR gene polymorphisms and renal cell cancer and breast cancer risks separately, through a systematic review of the present literature." (PMID 24297042, 2014).